TCF7L2 (transcription factor 7 like 2)
Diseases named in the same sentence as TCF7L2 in open-access papers (continued):
Sharing a sentence is not in itself a finding about the gene and the disease.
diabetes (continued). "Among candidate genes in association with T2DM, TCF7L2 is one of the strongest genes related to diabetes." (PMID 26587547, 2015). "The transcription factor 7-like 2 (TCF7L2) is one of the genes that have been identified as possible determinants of diabetes which is associated with obesity." (PMID 26608632, 2015). "Because HNF4α is a known master regulator of metabolic gene expression in the liver and is strongly associated with MODY forms of diabetes, we focused in more detail on the relationship between TCF7L2 and HNF4α at the molecular and genomic level." (PMID 25414334, 2014). "The TCF7L2 association with diabetes demonstrate that sufficiently powerful studies can generate statistically strong results (p < 10−8)." (PMID 24410812, 2014). "The key effector pathway of Wnt signaling (β-cat/TCF7L2) has beenrecently implicated in metabolic homoeostasis, diabetes, obesity, osteoporosis,cardiovascular disease, and cancer." (PMID 23617586, 2013). "Data from the Diabetes Prevention Program and the Diabetes Prevention Study indicate that lifestyle or environmental factors can modulate the genetic effects of TCF7L2 polymorphisms." (PMID 23306188, 2013). "For example, a 3-year follow-up study found that the risk allele homozygotes (TT) of TCF7L2 variant rs7903146 were more likely to develop diabetes from impaired glucose tolerance than the protective allele homozygotes." (PMID 23997649, 2013). "In our study we evaluated the association between the IVS4G>T mutation in the TCF7L2 gene with the presence of diabetes in patients with CF." (PMID 23050589, 2012). "In the family-based study, variation in TCF7L2 gene increased the risk of diabetes about threefold (HR 1.75 per allele, 95% CI 1.3–2.4; p = 0.0006), and decreased the mean age at diabetes diagnosis by 7 years." (PMID 23050589, 2012). "In our study we evaluated the association of the rs12255372 polymorphism (IVS4G > T mutation) in TCF7L2 gene with the presence of diabetes in patients with CF." (PMID 23050589, 2012). "Future prospective studies are needed to assess the relative risk of developing diabetes among subjects with TCF7L2 polymorphisms." (PMID 21441683, 2011). "Except for variants in the TCF7L2 gene which had a modest effect on diabetic risk, most genetic variants identified so far have only a weak association with diabetes." (PMID 24653947, 2011). "We recruited 189 patients with T2D being treated with SU agents and determined the TCF7L2 rs7903146 diabetes risk genotype, which has been reported as having the strongest association with T2D." (PMID 21349175, 2011). "Further, TCF7L2 SNPs rs12255372 and rs11196205 have been linked with impaired glucose metabolism and an increased diabetes risk." (PMID 21423583, 2011). "Our data suggest that patients with diabetes risk alleles in TCF7L2 have an altered hypoglycaemic response to SUs resulting in earlier secondary failure." (PMID 21349175, 2011). "Despite active research on the mechanism by which variation in TCF7L2 increases diabetes risk and affects β-cell function, the precise mode of action is poorly understood." (PMID 21814547, 2011). "In conclusion, present data strengthen previously reported findings suggesting altered therapeutic response to SUs in patients with T2D carrying the diabetes risk alleles at TCF7L2 variants." (PMID 21349175, 2011). "We previously showed that diabetes susceptibility variants in TCF7L2 were associated with early impairment of glucose tolerance in children before they develop overt diabetes." (PMID 21789219, 2011). "In the present study, we investigated the effect of TCF7L2 diabetes risk T-allele at rs7903146 on therapeutic response to SUs." (PMID 21349175, 2011). "These include transcription factors concerned with the control of: adipogenesis (Pparγ, Klf15, Irf1, Creb1, Egr2, Gata3); lipogenesis (Mlxipl, Srebp1c); inflammation (Jun, Stat3); insulin signalling and diabetes susceptibility (Foxo1, Tcf7l2)." (PMID 21187013, 2010).
diabetes (continued). "App and Tcf7l2, genes implicated in metabolic inflammation, Alzheimer's disease and diabetes are shown linked to their respective first neighbours." (PMID 21187013, 2010). "Nevertheless, given the scenario of established diabetes, coronary disease risk will be increased by itself, despite TCF7L2 genotype status." (PMID 19924244, 2009). "In this study, we aimed to confirm the effect of the TCF7L2 polymorphism rs7903146 on diabetes risk in a Brazilian population and to assess the use of this genetic marker in improving diabetes risk prediction in the general population." (PMID 19055834, 2008). "In a dominant model, the TCF7L2 SNP was modestly associated with diabetes risk (p = 0.099, OR = 1.31, 95% CI 0.95–1.81)." (PMID 18498660, 2008). "We genotyped four single nucleotide polymorphisms (SNPs) of TCF7L2 (rs7901695, rs7903146, rs11196205 and rs12255372) in 831 subjects with diabetes and 437 control subjects." (PMID 18291022, 2008). "Of 100K SNPs, one (rs7100927) was in moderate LD (r2 = 0.50) with TCF7L2 (rs7903146), and was associated with risk of diabetes (Cox p-value 0.007, additive hazard ratio for diabetes = 1.56) and with tFPG (GEE p-value 0.03)." (PMID 17903298, 2007). "While the exact mechanisms remain to be elucidated, continued research and the development of therapies targeting the TCF7L2 rs77961654 polymorphism could improve diabetes and cardiovascular health outcomes in genetically susceptible individuals." (PMID 40303486, 2025). "For example, the stage-specific enhancer of the diabetes-associated gene Transcription Factor 7 Like 2 (TCF7L2) drives its biphasic expression pattern during β-cell differentiation—a pattern that plays a key role in β-cell fate determination and functional maturation." (PMID 41303487, 2025). "It has been reported that the decreased insulin secretion function in diabetes is also associated with the variation of the TCF7L2 gene, and the TCF7L2 gene is associated with the pathogenesis of T2DM, possibly due to the decreased function of pancreatic β cells." (PMID 40225014, 2025). "Instead, our data suggest that in TCF7L2-associated diabetes, the loss of Tcf7l2 in the β-cells and adipose may be the primary drivers of diabetes, with low glutamine levels due to loss of Tcf7l2 in the hepatocytes as an aggravating factor." (PMID 40675550, 2025). "Though Tcf7l2 harbors the strongest genetic association with diabetes identified thus far, how it promotes metabolic disease remains unclear." (PMID 40675550, 2025). "The TCF7L2-mediated modulation of postprandial triglyceride metabolism may contribute to the risk of diabetes." (PMID 40870963, 2025). "In a 2-year study of lifestyle interventions (exercise and diet), diabetes-related TCF7L2 alleles were associated with weight loss caused by lifestyle interventions, and the diabetes-inducing effects of rs7903146 and rs12255372 on TCF7L2 were mitigated by lifestyle interventions." (PMID 40225014, 2025). "In addition to rs7903146, other TCF7L2 polymorphisms such as rs12255372, rs4506565, rs11196205, and rs11196218 have been associated with diabetes, glucose homeostasis, and cardiovascular conditions 30,31,46-48." (PMID 40303486, 2025). "Moreover, several studies have shown that TCF7L2 variants can predict diabetes risk in individuals with impaired glucose tolerance, consistent with the significantly elevated fasting glucose levels we observed in individuals carrying these genotypes." (PMID 40870963, 2025). "Also, polymorphisms in the TCF7L2 gene increases the risk of developing diabetes as TCF7L2 regulates the expression of ISL1, which is required for proinsulin synthesis." (PMID 38671406, 2024). "The TCF7L2 gene, known to influence pancreatic β-cell function and insulin secretion, plays a significant role in glucose homeostasis, making it a crucial genetic marker in the context of diabetes risk." (PMID 39469345, 2024).
diabetes (continued). "Since genotype at rs7903146 was known in these cohorts, we also show that diabetes-associated genetic variation in TCF7L2 seems to have a greater effect on raising peak glucose concentrations as well as impairing the suppression of postchallenge glucagon concentrations." (PMID 39011323, 2024). "Next, we analyzed the correlation between these 13 DN genetic variation sites related to intestinal microbes and clinical phenotypes and found that the risk genotype of TCF7L2 rs4277044-AG was associated with a longer diabetes duration and higher diastolic blood pressure." (PMID 38189041, 2023). "It is known that polymorphisms at TCF7L2 are strongly associated with risk of diabetes, obesity, and other metabolic disturbances, hinting that our results may be relevant for human disease." (PMID 37909330, 2023). "For example, the TCF7L2 risk genotype was associated with a long duration of diabetes and high diastolic blood pressure, the ZCWPW2 risk genotype was associated with a high level of HbA1c, and the ZNRF3 risk genotype was associated with an elevated urinary microalbumin-to-serum ratio." (PMID 38189041, 2023). "Therefore, Tcf7l2-deficient in vitro and in vivo models are being used to track the association between SNPs in Tcf7l2 and Tcf7l2 expression, and to gain insights into diabetes-related molecular pathways." (PMID 36759348, 2023). "In addition, their findings link obesity, diabetes and genetic susceptibility involving the TCF7L2 and MTNR1B genes." (PMID 36532520, 2022). "The TCF7L2 protein, a key transcriptional effector of the Wnt/β-catenin signaling pathway, which regulates gene expression, is associated with numerous diseases such as cancer, diabetes, and small intestinal Crohn’s disease." (PMID 35558081, 2022). "In addition, genome-wide association studies indicated a correlation between transcription factor 7 like 2 (TCF7L2) polymorphism and the development of diabetes and DKD." (PMID 35966076, 2022). "This prompted us to ascertain if postprandial triglycerides dysmetabolism could be an important and novel mechanism by which TCF7L2 associated risk of diabetes is mediated." (PMID 36263318, 2022). "Modulation of PPTg metabolism by TCF7L2 gene and the resultant PPHTg may be a novel mechanism that contributes to its diabetes risk in them." (PMID 36263318, 2022). "rs7903146 in TCF7L2 is another common genetic variant highly associated with diabetes." (PMID 33919522, 2021). "In fact, a family study highlighted that a family history of T2D increases the risk of diabetes in individuals with CF and that a variant in the transcription factor 7-like 2 (TCF7L2) gene, known to be associated with T2D prevalence in the general population, is also involved in CFRD." (PMID 33810109, 2021). "Previous studies of the relationship between TCF7L2 expression and glucose homeostasis have suggested that the combined effects of loss of TCF7L2 in multiple tissues may underlie exaggerated diabetes risk." (PMID 33068125, 2021). "In addition, it would be preferable to study all other SNPs of the TCF7L2 gene in our population which can potentially reveal the presence of other links with the susceptibility of developing diabetes and their complications." (PMID 34073870, 2021). "As improper use of corticosteroids can induce the occurrence of GPP or diabetes, the relationship between TCF7L2 variants and GPP may occur due to glucose metabolism." (PMID 35664972, 2021). "Furthermore, in addition to nine diabetes-associated genes, five in seven TCF7L2 splice forms were differentially expressed by comparing leukocyte cells of carriers of the CC and CT/TT genotypes." (PMID 33996288, 2021). "Thus the overall mechanism, how transcription factor TCF7L2 and in particular rs7903146 impacts the metabolic state and is associated with diabetes has been intensively discussed in the past." (PMID 31492908, 2019).
diabetes (continued). "Interestingly, some ATAC-seq peaks overlapping with both these marks are annotated to genes that have islet specific function and/or have been associated with diabetes by GWAS e.g., TCF7L2, SLC2A2, FOXO1 and HNF1B27." (PMID 31123324, 2019). "It provides a first hint that the well-known impact of the TCF7L2 polymorphism rs7903146 on diabetes risk may, at least in part, be dependent on serotonin regulation mediated by the Wnt signalling pathway." (PMID 31492908, 2019). "It has to be mentioned that there are further mechanism by which TCF7L2 might impact the diabetes risk, and some of these mechanism may be independent from Wnt signalling." (PMID 31492908, 2019). "A recent study has shown that along with reduced insulin secretion, decreased glucagon suppression may contribute to the predisposition to diabetes conferred by TCF7L2." (PMID 30700996, 2019). "Finally, the presented link between TCF7L2 and serotonin is biologically plausible, and the association between TCF7L2 and diabetes on the one hand and the association between serotonin and diabetes on the other hand are already known." (PMID 31492908, 2019). "In addition, expression of the proglucagon gene (which encodes GLP-1) in the brain is regulated by transcription factor 7 like 2 (TCF7L2), which is associated with the risk of diabetes." (PMID 30423881, 2018). "Furthermore, the downstream molecule of the diabetes risk genes, TCF7L2, is associated with schizophrenia." (PMID 29713286, 2018). "Genome-wide association studies have identified diabetes-associated genes (e.g. TCF7L2) that may also contribute to colorectal cancer." (PMID 28060743, 2017). "TCF7L2 is the most powerful, recognized susceptibility gene for diabetes." (PMID 27108846, 2016). "It should be mentioned here that rat Tcf7l2, and the exclusively pancreatic islet expressed Slc30a8, whose variants confer both diabetes risk and protective effects and whose autoantibodies are detected in T1D patients, have targeted mutations introduced via zinc finger nuclease (ZFN) mutagenesis." (PMID 27602200, 2016). "First, most of the included studies were designed to study the association of TCF7L2 variants with diabetes, hyperglycemia, and coronary artery disease and only 2 studies were exclusively designed to examine the association between rs7903146 and plasma lipid levels." (PMID 26576435, 2015). "Recently, much effort has been devoted to elucidating how the T2D-associated SNP rs7903146, which lies in intron 3 of the T-cell factor 7 like-2 (TCF7L2) gene, may lead to increased risk of diabetes." (PMID 25355422, 2015). "Among genetic variants, the diabetes-associated variants in TCF7L2 (rs7903146) and WFS1 (rs10010131) have been shown to affect the response to exogenous GLP-1, while variants in KCNQ1 (rs151290, rs2237892, and rs2237895) have been reported to alter endogenous GLP-1 secretion." (PMID 25785276, 2015). "TCF7L2 as the diabetes-susceptibility gene may increase the risk of chronic kidney disease not only through its effect on diabetes but also through some renal-specific mechanisms." (PMID 24574000, 2014). "The Diabetes Prevention Program and the Finnish Diabetes Prevention Study provided the first indications that environmental or lifestyle factors might influence the genetic effect of TCF7L2 polymorphisms." (PMID 25491720, 2014). "The mechanisms by which TCF7L2 polymorphisms increase diabetes risk and affect the treatment response to insulin secretagogues were thought to be related to impaired incretin-induced insulin secretion, impaired suppression of glucagon or impaired glucagon-like peptide-1 secretion." (PMID 24906949, 2014). "Investigation of the mechanisms by which TCF7L2 rs7903146-macronutrient interactions affect the T2D risk might yield new insights into the molecular basis of diabetes and thus provide opportunities for more targeted preventive and therapeutic interventions." (PMID 25491720, 2014).
diabetes (continued). "Savic and colleagues took a different approach whereby they engineered mice that expressed LacZ under the control of human bacterial artificial chromosomes (BACs) containing the genomic interval encompassing the diabetes associated SNPs (which are intronic) for TCF7L2." (PMID 23710470, 2013). "where high (n-6) polyunsaturated fatty acids intakes were associated with atherogenic dyslipidemia in carriers of the minor T allele at rs7903146 SNP in the TCF7L2 gene and may predispose them to Metobolic Syndrome (MetS), diabetes, and cardiovascular disease." (PMID 23244446, 2012). "Taken together with a recent report indicating that dietary fiber may alter the association between TCF7L2 and diabetes, it remains possible that changing certain components of the diet, such as fiber intake, may alter risks associated with TCF7L2 variants." (PMID 21814547, 2011). "Except for variants in the TCF7L2 gene which had a modest effect on diabetic risk (odds ratio 1.40–1.56), most genetic variants identified so far have only a weak association with diabetes (odds ratios ranging from 1.1 to 1.3)." (PMID 24653947, 2011). "Also noteworthy, given the TCF7L2 diabetes risk genotypes make patients more resistant to the action of sulfonylureas, one would expect that carriers of the risk genotype should be less likely to become hypoglycaemic." (PMID 21349175, 2011). "Framingham 100K data replicate the TCF7L2 association with diabetes." (PMID 17903298, 2007). "Our finding of higher rates of microvascular complications in T allele patients with diabetes is consistent with specific dysfunction of insulin production in the beta cell present with the TCF7L2 polymorphism, perhaps leading to greater exposure to hyperglycemia-mediated damage." (PMID 17181866, 2006). "Our study aimed to investigate whether the presentation of diabetes and related features is associated with TCF7L2 genotype in a representative population of older people." (PMID 17181866, 2006). "TCF7L2 minor allele carrier patients with diabetes are less likely to have metabolic syndrome features, but may be at higher risk from more microvascular complications, including renal impairment and (vascular) dementia." (PMID 17181866, 2006). "Additionally, genes such as TCF7L2 have been associated with glucose homeostasis and insulin signaling pathways, suggesting a potential role in the metabolic dysregulation observed in diabetes and its complications." (PMID 40692573, 2025). "Most included observational studies had been conducted among subjects with non-diabetes, and in most of them, insulin resistance was further impaired with high consumption of fatty acids or high concentration of plasma fatty acids in risk allele carriers of TCF7L2." (PMID 36155628, 2022). "Therefore, we aimed to study the polymorphisms of TCF7L2 gene and its expression in subcutaneous and visceral adipose tissue to find out its association with postprandial hypertriglyceridaemia and risk of diabetes in subjects with varying degree of glucose tolerance." (PMID 36263318, 2022). "Furthermore, SNPs in the TCF7L2 gene have been associated with obesity and diabetes." (PMID 36532520, 2022). "Additionally, the diabetes gene and Wnt pathway effector TCF7L2 may increase susceptibility to both diabetes and kidney disease." (PMID 35795641, 2022). "It has been observed that TCF7L2 influences regulation of glucose metabolism through the Wnt signaling pathway and that carriers of the double risk allele (T/T) were more likely to have progression from impaired glucose tolerance to diabetes than were CC homozygotes and decreased insuline secretion." (PMID 35010944, 2021). "Diabetes and chronic kidney disease have an inflammatory response component in common and since the Wnt signaling pathway is involved in this response, studying a role of TCF7L2 gene variants in both diseases can improve the understanding of mechanisms involved in affecting disease risk." (PMID 24574000, 2014).